CDK7 (cyclin dependent kinase 7)
Diseases named in the same sentence as CDK7 in open-access papers (continued):
Sharing a sentence is not in itself a finding about the gene and the disease.
cancer (continued). "Although screening data was not available for THZ1, THZ2, a THZ1-derived analogue with similar CDK7 selectivity, has been screened using this cancer cell line panel." (PMID 31530935, 2020). "The recently developed, highly specific inhibitors of CDK7 have been instrumental in revealing the potential of CDK7 as a cancer drug target." (PMID 32385714, 2020). "Following emergence of the concept of super enhancers in cancers, the means to target them effectively were discovered, and the CDK7/12 inhibitor, THZ1, was amongst the most promising drugs." (PMID 32752193, 2020). "Because of its dual role in regulating the cell cycle and transcription, CDK7 has been studied as an anticancer drug target, and a number of selective inhibitors of CDK7 have been developed and investigated as cancer therapies." (PMID 32385714, 2020). "Overall, there is much potential for CDK7 inhibitors to be used in combination with other drugs for cancer therapy." (PMID 32385714, 2020). "THZ1, a relatively selective covalent inhibitor of CDK7, effectively inhibits the growth of several cancer types such as T-cell acute lymphoblastic leukemia, MYCN-amplified neuroblastoma, and small cell lung cancer." (PMID 31462705, 2020). "Recent studies have demonstrated that some inhibitors (such as JQ1 and CDK7) selectively kill cancer cells by inhibiting SE-driven oncogene transcription." (PMID 32128448, 2020). "CDK7 has previously been reported to be a therapeutic target in cancers driven by MYC and THZ1 has consistently been shown to decrease the expression of MYC protein and mRNA." (PMID 32155786, 2020). "Responses of 386 human cell lines, encompassing 26 cancer types, to the covalent CDK7 inhibitor SY-1365, revealed varied responses ranging from cytostatic to highly cytotoxic." (PMID 32385714, 2020). "At least ten selective inhibitors of CDK7, with activity against a wide range of cancer types, have been developed, their antitumour action likely mediated both through cell cycle arrest and inhibition of oncogenic transcriptional programs." (PMID 32385714, 2020). "THZ1, a recently identified covalent CDK7 inhibitor, displays high therapeutic potency in a variety of cancers." (PMID 32174795, 2020). "THZ1 is a covalent inhibitor of CDK7, which shows strong antitumor effects in various cancers by inhibition of CDK79–16." (PMID 31399555, 2019). "Treatment with CDK7 inhibitors reduced the gene expression and inhibited proliferation in cancer cell lines and animal models." (PMID 31076643, 2019). "Of note, the elevated CDK7 was found most significant in CCA compared with other cancers in the TCGA database." (PMID 31399555, 2019). "In recent years, several researchers demonstrated that CDK7 was overexpressed in different cancers and correlated with poor prognosis." (PMID 31399555, 2019). "CDK7 is considered as an attractive target for treating human cancer, as it controls the activity of key enzymes involved in cell cycle progression, including other cyclin-dependent kinases such as CDK1, CDK2, CDK4, and CDK6." (PMID 31076643, 2019). "We and others have recently reported the growth inhibitory effects of THZ1 in multiple types of cancers via suppressing CDK7-dependent transcriptional activation." (PMID 30496486, 2019). "THZ1, a specific covalent inhibitor of CDK7, selectively blocks the transcription of super-enhancer-associated oncogenes, such as MYC, MYCN, YAP1, and RUNX1, thereby inducing cancer cell growth inhibition and apoptosis." (PMID 31346162, 2019). "Despite repeated attempts, the knockdown efficiency of CDK7 we were able to achieve in H460 cells was moderate, possibly due to the essential nature of this protein for cancer and other dividing cell populations." (PMID 31784510, 2019). "Since the cell lines screened with this library are derived from various different tissues and cancer types, a common resistance to CDK7 knockout seems unlikely." (PMID 29467179, 2018).
cancer (continued). "Interestingly, levels of Cyclin dependent kinase 7 (Cdk7) were also strongly reduced upon Cbp80 knockdown and Piwi proteins had previously been implicated in the upregulation of the expression of Cdks and Cyclins and in enhancing cell proliferation in several cancers." (PMID 28746365, 2017). "It largely and irreversibly inhibited Cdk7 activity in cultured primary neurons, in a temporal pattern and at a concentration similar to that in stems cells and cancer cells." (PMID 29163040, 2017). "Nevertheless, inhibition by small molecules inhibiting Cdk5 and additionally Cdk1, Cdk2, Cdk7, and Cdk9 have shown promising effects in cancer/angiogenesis." (PMID 26755662, 2016). "Recent studies reported that many cancer cell lines are sensitive to Cdk7 inhibitors, which reduce RNA pol II Ser-5 phosphorylation." (PMID 27756891, 2016). "As an important component of CAK, CDK7 is a promising therapeutic target for a variety of anti-carcinoma chemotherapeutic regimens." (PMID 25411854, 2015). "Emerging strategies-such as BET inhibitors, CDK7/9 inhibitors, and rational drug combinations-effectively disrupt SE-driven transcriptional programs and show potential to overcome treatment resistance in these cancers." (PMID 41268574, 2025). "SE-driven genes, such as MYC, are particularly upregulated in cancer and are challenging to target directly, but this difficulty might be overcome by targeting CDK7.347–349 Studies in multiple types of cancer support this hypothesis." (PMID 39800748, 2025). "Also relevant from a therapeutic point of view, we explored the ability of CDK7-selective inhibitors to effectively target and eradicate cancer stem cells (CSC)-enriched HNSCC tumorsphere cultures." (PMID 41193441, 2025). "We also provide proof of concept that CDK7 inhibitors developed for human cancer treatment, including two that are orally administered, could be repurposed or dual-purposed as antifungal agents when combined with licensed antifungals." (PMID 41171060, 2025). "Future research should prioritize validating these findings in more complex preclinical settings, exploring combinational therapies such as CDK7 inhibitors alongside other targeted agents, and translating these insights into clinical trials targeting this aggressive pediatric cancer subtype." (PMID 40943594, 2025). "Given that CDK7 is upregulated in cancer cells, CDK7 inhibitors are emerging as a promising chemotherapeutic option to minimize side effects, with some inhibitors having entered clinical trials to treat a variety of cancers." (PMID 41171060, 2025). "Furthermore, dual CDK4/6 and CDK7 inhibition stimulates immune-related signaling and cytokine production in cancer cells, promoting anti-tumor immune responses within the tumor microenvironment." (PMID 40794455, 2025). "In addition, the covalent cyclin-dependent kinase 7 (CDK7) inhibitor THZ1 inhibits cancer stemness by disrupting SHH signaling." (PMID 40635786, 2025). "For a follow-up study of IB, we explored the association of CDK7/9 expression with TNBC and evaluated whether IB has anti-cancer efficacy and can inhibit metastasis in TNBC." (PMID 38892310, 2024). "However, resistance to treatments with BETis and CDK7 inhibitors has been observed in many cancer cells." (PMID 38844984, 2024). "The development of therapies targeting CDK7 is ongoing for various cancers." (PMID 38892310, 2024). "Recently, pharmacologic inhibition of Cdk7 has emerged as a promising option for cancer treatment." (PMID 39097586, 2024). "With the emergence of Cdk7 as a potential vulnerability in cancer cells, a deeper understanding of its regulators might yield additional therapeutic opportunities." (PMID 39097586, 2024). "Therefore, CDK7/9 represent good anti-cancer targets because of their involvement in regulating the cell cycle and transcription." (PMID 38892310, 2024). "Therefore, targeting CDK7, which regulates the transcription process, has emerged as a new promising approach for treating cancer." (PMID 39386027, 2024).
cancer (continued). "CDK7 is expected to become an important target for cancer treatment." (PMID 38640110, 2024). "Taken together, these data demonstrated that highly expressed CDK7/9 may play a role in metastasis and survival of TNBC cells and suggest that CDK7/9 may be a good anti-cancer target for TNBC." (PMID 38892310, 2024). "THZ1 is an inhibitor of cyclin-dependent kinase 7 (CDK7), an enzyme involved in the regulation of cell cycle progression and linked to increased transcription of oncogenes and increased proliferation rate of cancer cells." (PMID 37287910, 2023). "Such therapies could provide a complementary approach to treat TNBC as well as other cancers where CDK7 inhibitors induce genome instability, such as the recently reported effects in SCLC and HCC." (PMID 37201585, 2023). "CDK7 play a critical role in mediating the transcription of key cancer dependence genes." (PMID 37476070, 2023). "Multiple studies indicating aberrant expression of CDK7 in cancer have been reported." (PMID 37342192, 2023). "In this context, co-targeting of CDK7 and P-TEFb could be beneficial in the tug-of-war, particularly because cancer cells evolve a multiplicity of strategies to short-circuit both modes of apoptosis activation." (PMID 36727434, 2023). "While Cdk7 inhibition has been shown to have anti-cancer effects by blocking cell cycle progression and inducing apoptosis, it may also negatively affect normal cells and tissues." (PMID 37108171, 2023). "The CRPC-selective anomalies that initially conferred the growth advantage to cancer cells may explain why these cells are addicted on the high CDK7 activity." (PMID 36401094, 2023). "In addition, Atuveciclib, a selective PTEFb/CDK9 inhibitor, and CT7001, a selective CDK7 inhibitor, are emerging as potential cancer treatment options, as they have entered clinical trials." (PMID 37842645, 2023). "Finally, we discuss clinical significance of the CRISPR-Cas9 gene editing system and inhibitors of SE-related proteins such as BET and CDK7 as potential cancer therapeutics." (PMID 36923930, 2023). "Further analysis through published RNA-seq data found that poly(A) read-through analogous and NEAT1_2 splicing induction are analogous to IAV and HSV-1 infection in cancer cells upon knockdown of CDK7 or MED1 subunit of the Mediator complex that was phosphorylated by CDK7." (PMID 37489458, 2023). "The CDK7 inhibitor THZ1 exerts antitumorigenic effects in various cancers." (PMID 36076237, 2022). "THZ1, a CDK7 inhibitor, exhibits a dose-dependent inhibitory effect in various cancers." (PMID 36076237, 2022). "Interestingly, we found that selective CDK7 inhibition by THZ1 also disrupts transcription termination in cancer cell lines, albeit less strongly than HSV-1 and H5N1 infection." (PMID 36279270, 2022). "For example, THZ1, a covalent CDK7 inhibitor, has a suppressive effect on many cancer cells." (PMID 36058938, 2022). "Since CDK7, CDK8/19, CDK12/13, or CDK9 are associated with basal RNA transcription, it seemed a reasonable strategy to selectively target these CDKs, as cancer cells may be particularly susceptible to selective suppression." (PMID 35053461, 2022). "The inhibition of CDK7 can target cancer cells, leading to their apoptosis." (PMID 35879772, 2022). "These shreds of evidence suggest that CRISPR/Cas9 could be used as a therapeutic tool to target CDK7 in controlling cancer cell growth." (PMID 35879772, 2022).
cancer (continued). "Considering that CDK7 inhibitors are currently tested in several trials for advanced solid malignancies, it may also be a new target for future anti-cancer therapy." (PMID 36212402, 2022). "Furthermore, CDK7 expression tended to be higher in primary carcinomas that later recurred compared to primary tumors that showed no relapse (p 0.34)." (PMID 36212402, 2022). "Furthermore, emerging evidence has revealed that inhibiting CDK7 has anti-cancer effects, driving the development of novel and more cost-effective inhibitors with enhanced selectivity for CDK7 over other CDKs." (PMID 34572383, 2021). "Since CDK7 plays such a critical role in cell proliferation and transcription, there is a constant need for research to find effective inhibitors that can control overexpression and combat emerging cancer resistance." (PMID 34572383, 2021). "Again, it is apparent that factors influencing the effect of CDK7 inhibition on cell cycle progression across different cancers remain to be identified and these may have an important impact on the clinical use of these inhibitors." (PMID 32385714, 2020). "In addition, THZ1 and related compounds that inhibit the kinase activity of CDK7 by binding a protein region outside of its catalytic domain (Cys312) are very effective in killing different types of cancer cells." (PMID 31963603, 2020). "CDK7, a transcriptional cyclin-dependent kinase, is emerging as a novel cancer target." (PMID 32155786, 2020). "Recently, these findings have become embodied in a wider framework known as “Transcription addiction in cancer”, a concept that supports CDK7 as a potentially valuable cancer drug target, as it plays key roles in both the regulation of transcription and the cell cycle." (PMID 31530935, 2020). "BRD4 and CDK7 are essential components of SEs in various cancers." (PMID 33298918, 2020). "Targeting TFIIH subunits, such as CDK7, has been a promising strategy in cancer treatment." (PMID 32690037, 2020). "Additionally, combining the treatments that promote protein degradation and a CDK7 inhibitor THZ1 has the potential for developing a synthetic-lethal therapy for more effective cancer treatment." (PMID 32143485, 2020). "The prospect of using CDK7 inhibitors to overcome resistance to prior treatments in cancer is exciting, and it is crucial that information garnered from preclinical studies of CDK7 inhibitors in the context of acquired drug-resistance continues to be considered during clinical trial design." (PMID 32385714, 2020). "The emergence of resistance to cancer treatment, including targeted therapies, remains a major issue, and it is possible that even if CDK7 inhibitors prove a clinical success, resistance may develop in some patients." (PMID 32385714, 2020). "In addition to cell cycle arrest, apoptosis is observed following CDK7 inhibition, in numerous cancer types, including solid tumours and haematological malignancies." (PMID 32385714, 2020). "THZ1 was discovered as a covalent CDK7 inhibitor, with a promising potential in cancer treatment." (PMID 32143485, 2020). "THZ1, a selective covalent inhibitor of CDK7, has antitumor effects in several human cancers." (PMID 31752390, 2019). "Thus, the development of selective CDK7 inhibitors for cancer treatment has received widespread attention, and some CDK7 inhibitors currently are being examined in preclinical or clinical studies as cancer therapeutics." (PMID 31076643, 2019). "CDK7 inhibitor THZ1 has been proposed as potential treatment for several types of cancer." (PMID 29163040, 2017). "Considering the multiple roles of CDK7 in normal and cancer cells, namely to perpetuate their lineage, to give rise to differentiated cells, and to interact with their environment, it has been considered a target in drug-resistant human cancers and particularly TNBC." (PMID 38930141, 2024).
cancer (continued). "Therefore, we decided to explore whether Cdk7 inhibition in cancer cells also induced the formation of DoGs." (PMID 38250805, 2024). "Upregulation of HSP70 by ML346 induced cell paraptosis in a CDK7/CDK9-dependent manner, while selective inhibition of HSP70 by 2-phenylethynesulfonamide impaired the function of associated chaperones and resulted in cell paraptosis in several cancer cell lines." (PMID 38858714, 2024). "In addition to CDK12, CDK7 inhibitor sensitizes DDR-proficient cancer cells to PARP inhibitor." (PMID 37342192, 2023). "Thus, inhibiting CDK7 in cancer cells may be a potential approach to activate the macrophage immune response." (PMID 37476070, 2023). "Therefore, effective CDK7-targeted anti-cancer therapyrequires further verification in the future." (PMID 36923930, 2023). "Notably, MYC‐driven cancers were shown to be more susceptible to splicing inhibition, suggesting that the effects of CDK7 on splicing regulation may contribute to its oncogenic role in cancers that rely on MYC." (PMID 34092037, 2021). "Similarly, considering that CDK7 promotes YAP stabilization (and activity) by directly phosphorylating and preventing their degradation, preclinically available CDK7 inhibitors could be considered to blunt YAP/TAZ-dependent transcription in cancer cells." (PMID 34439395, 2021). "Therefore, CDK7 has been identified as a promising drug target for cancer treatment." (PMID 33476598, 2021). "Indeed, CDK7 was found to be associated with the important transcription factor MYC and with the STAT3 and β-catenin pathways which play crucial roles in tamoxifen resistance, stemness, and cancer progression." (PMID 32340192, 2020). "The phenomenon of transcriptional addiction suggests that cancer cells may be more responsive than normal cells to transcriptional inhibition and provides a strong basis for targeting transcriptional kinases, including CDK7, in cancer." (PMID 32385714, 2020). "However, despite extensive studies on the roles of Cdks in cells undergone frequent cell cycles, such as cancer cells and stem cells, the role of Cdk7 in the regulation of transcription remains unknown in post-mitotic neurons." (PMID 29163040, 2017). "Therefore, CDK7 was hypothesized to be a novel target for a variety of anti-carcinoma drug treatments." (PMID 25411854, 2015). "This investigation demonstrated that kaempferol affects cancer cells by downregulating CDK1, CDK4, CDK6, and CDK7 at both the gene and protein levels in MDA-MB-231 cells, and specifically CDK6 and CDK7 in MDA-MB-468 cells." (PMID 41463161, 2025). "Another potent and orally bioavailable covalent CDK7-selective inhibitor, XL102 (formerly known as AUR102), has shown promise as an anti-cancer therapy." (PMID 40163908, 2025). "CDK7, CDK8, and CDK9 are desirable targets for therapy since they have shown oncogenic roles in a variety of cancer types, such as colorectal, ovarian, and breast malignancies." (PMID 40361480, 2025). "Several CDKs, such as CDK4, CDK7, CDK9, and more recently CDK12, have been closely studied for their involvement in cancer progression." (PMID 40996961, 2025). "While CDK7 and CDK9 pathways have recently been targeted in cancer treatment, further elucidation is required regarding their involvement in the paraptotic program." (PMID 38858714, 2024). "The TFIIH complex subunit cyclin-dependent kinase 7 (CDK7), which controls the cell cycle and initiates transcription by Pol II, has emerged as a brand-new target for treating cancer." (PMID 38681203, 2024). "In the field of cancer therapy, inhibitors of SE complex proteins, such as BRD4, CDK7, or CDK9, show great potential." (PMID 37501079, 2023).